CYP3A7 (cytochrome P450 family 3 subfamily A member 7)
Description:
A cytochrome P450 monooxygenase involved in the metabolism of steroid hormones and vitamins during embryogenesis. Mechanistically, uses molecular oxygen inserting one oxygen atom into a substrate, and reducing the second into a water molecule, with two electrons provided by NADPH via cytochrome P450 reductase (NADPH--hemoprotein reductase). Catalyzes the hydroxylation of carbon-hydrogen bonds. Metabolizes 3beta-hydroxyandrost-5-en-17-one (dehydroepiandrosterone, DHEA), a precursor in the biosynthesis of androgen and estrogen steroid hormones. Exhibits high catalytic activity for the formation of hydroxyestrogens from estrone (E1), particularly D-ring hydroxylated estrone at the C16-alpha position. Mainly hydroxylates all trans-retinoic acid (atRA) to 4-hydroxyretinoate and may play a role in atRA clearance during fetal development. Also involved in the oxidative metabolism of xenobiotics including anticonvulsants.
Synonyms: CP37; P450-HFLA; CYPIIIA7; P-450(HFL33); P-450111A7; P450HLp2
Tractability: Small molecule: an approved drug acts on it; a structure with a bound ligand is known; it belongs to a druggable protein family. Antibody: UniProt places it where antibodies can reach, with medium confidence. PROTAC: its protein half-life has been measured; a small molecule that binds it is known.
Target class: Enzyme; Oxidoreductase
Gene: Protein-coding gene on chromosome 7 (99,705,036 to 99,735,196, reverse strand). Ensembl gene ENSG00000160870.
Subcellular location: Endoplasmic reticulum membrane; Microsome membrane
Subcellular location (Human Protein Atlas): Cytosol; Vesicles
Pathways (Reactome):
Metabolism: Xenobiotics
Gene Ontology:
Molecular function: all-trans retinoic acid 18-hydroxylase activity; estrogen 16-alpha-hydroxylase activity; estrogen 2-hydroxylase activity; oxidoreductase activity, acting on paired donors, with incorporation or reduction of molecular oxygen, reduced flavin or flavoprotein as one donor, and incorporation of one atom of oxygen; retinoic acid 4-hydroxylase activity; steroid hydroxylase activity; testosterone 6-beta-hydroxylase activity; monooxygenase activity; oxygen binding; heme binding; iron ion binding; oxidoreductase activity, acting on paired donors, with incorporation or reduction of molecular oxygen
Biological process: estrogen metabolic process; lipid hydroxylation; retinoic acid metabolic process; steroid metabolic process; oxidative demethylation; xenobiotic metabolic process; retinol metabolic process
Cellular component: endoplasmic reticulum membrane
Genetic constraint (gnomAD): Loss-of-function variants: 46 observed, 56.9 expected, observed/expected ratio (o/e) 0.81, 90% interval 0.64 to 1.03. The upper end of that interval is the gene's LOEUF score, 1.03, which puts it in group 4 of 6, group 1 being the genes least tolerant of losing a copy. Missense variants: 548 observed, 628.11 expected, observed/expected ratio (o/e) 0.87, 90% interval 0.81 to 0.94. Synonymous variants: 180 observed, 214.53 expected, observed/expected ratio (o/e) 0.84, 90% interval 0.74 to 0.95.
Homologues: Orthologues: macaque CYP3A7 (91% identical), dog CYP3A26 (75% identical), dog CYP3A12 (75% identical), rat Cyp3a9 (73% identical), dog CYP3A26 (72% identical), mouse Cyp3a13 (72% identical), pig CYP3A29 (72% identical), mouse Cyp3a11 (70% identical), rat Cyp3a23-3a1 (69% identical), guinea pig Cyp3a14 (69% identical), mouse Cyp3a41a (69% identical), mouse Cyp3a41b (69% identical), and 17 more. Paralogues in human: CYP3A4 (88% identical), CYP3A5 (82% identical), CYP3A43 (71% identical).
Diseases named in the same sentence as CYP3A7 in open-access papers:
CYP3A7 is named in the same sentence as 15 diseases in open-access papers, as found by Europe PMC text mining. Sharing a sentence is not in itself a finding about the gene and the disease. The quoted sentences say what the papers report.
breast carcinoma (6 papers, 2012 to 2022). "The CYP3A7 gene affects the metabolism of endogenous sex hormones (oestrone and progesterone) in premenopausal women, and due to this, it can determine breast cancer risk." (PMID 36430184, 2022). "Our analysis supports these conclusions if we assume that breast cancer risk in carriers of the CYP3A7*1C allele is influenced by two components with opposite effects." (PMID 28072767, 2017). "Based on the combined evidence of prospective studies of premenopausal hormone levels and breast cancer risk, lifetime lower levels of E1 and E2 of ∼45% and 27% in carriers of the CYP3A7*1C allele would be predicted to result in a substantial reduction in risk for these individuals." (PMID 28072767, 2017). "The CYP genes with the lowest expression in the TCGA breast cancer cohort were: CYP1A2 (0.010), CYP3A43 (0.029), CYP3A7 (0.033), CYP2C9 (0.044) and CYP3A4 (0.044)." (PMID 28684774, 2017). "We found that expressions of certain CYP genes is correlated with node status (N stage) of breast cancer including CYP2A6 (p-value = 0.025), CYP2C8 (p-value = 0.035), CYP2D6 (p-value = 0.027), CYP2J2 (p-value = 0.036), CYP3A7 (p-value = 0.026), and CYP4B1 (p-value = 0.046)." (PMID 28684774, 2017).
hepatocellular carcinoma (4 papers, 2014 to 2025). A malignant tumor that arises from hepatocytes. "CYP3A7 is reportedly overexpressed in hepatocellular carcinoma." (PMID 41154660, 2025). "Conversely, overexpression of CYP3A7 was witnessed in hepatocellular carcinoma, suggesting that it might exert varied functions among different types or stages of tumor." (PMID 32789468, 2020). "However, CYP3A7 is preferentially expressed in premature hepatoblasts and major hepatic carcinoma cell lines." (PMID 25101946, 2014). "For example, ARG1, CYP2C8, CYP3A4, CYP3A7 and CYP4A11, which we identified using MOG as decreasing expression with LIHC progression, have each been recently studied as prognostic markers for hepatocellular carcinoma." (PMID 31956905, 2020).
endometriosis (2 papers, 2022 to 2023). The growth of functional endometrial tissue in anatomic sites outside the uterine body. "The results showed that SNP sites such as AKR1C2 (rs116900756), AKR1D1 (rs9642092), CYP11B1 (rs1134095), CYP3A7 (rs45446698) appeared simultaneously in the MR analysis results of TT and BioT on ovarian cancer, endometrial cancer, endometriosis, PCOS and POF." (PMID 38075074, 2023).
Hypertension (2 papers, 2012 to 2023). The presence of chronic increased pressure in the systemic arterial system. "The corresponding metabolites may represent a molecular link between genetic variants and clinical endpoints, as detailed for genetic variants at the CYP3A7 locus that colocalized with plasma androsterone sulfate levels and hypertension in the Supplementary Results." (PMID 37277652, 2023). "The ancestral alleles of these SNPs have previously been associated with the nutrition-related diseases hypertension (AGT and CYP3A7) and insulin resistance (ENPP1)." (PMID 23036011, 2012).
ovarian carcinoma (2 papers, 2023). A malignant neoplasm originating from the surface ovarian epithelium. "In contrast, high mRNA expression of CYP2A6, CYP2C9, CYP2J2, CYP3A4, CYP3A5, CYP3A7, and CYP3A43 connoted a good prognosis for ovarian cancer patients." (PMID 38001897, 2023).
Insulin resistance (1 paper, 2012). Increased resistance towards insulin, that is, diminished effectiveness of insulin in reducing blood glucose levels. "The ancestral alleles of these SNPs have previously been associated with nutrition-related diseases hypertension (AGT and CYP3A7) and insulin resistance (ENPP1)." (PMID 23036011, 2012).
leukemia (1 paper, 2017). A malignant (clonal) hematologic disorder, involving hematopoietic stem cells and characterized by the presence of primitive or atypical myeloid or lymphoid cells in the bone marrow and the blood. "For example, an allele of CYP3A7 is associated with poor outcomes in leukemia, breast and lung cancers." (PMID 28765560, 2017).
lung carcinoma (1 paper, 2022). "CYP3A7 expression can also be found in a subset of the adult population who carry the CYP3A7*1C allele, which is associated with lower levels of dehydroepiandrosterone sulfate (DHEAS) in men and is linked to mortality in breast and lung cancers." (PMID 35847040, 2022).
polycystic ovary syndrome (1 paper, 2025). A disorder that manifests as multiple cysts on the ovaries. "Indeed, polycystic ovary syndrome (PCOS) patients carrying the CYP3A7*1 C variant – indicative of persistent expression of CYP3A7 through to adulthood – have lower androgen concentrations than PCOS noncarrier patients, which may overall dampen androgen signalling pathways." (PMID 41204352, 2025).
cancer (5 papers, 2020 to 2024). A tumor composed of atypical neoplastic, often pleomorphic cells that invade other tissues. "Understanding CYP3A7-related metabolism may also aid in developing more effective cancer therapeutics where elevated CYP3A7 expression is implicated." (PMID 35847040, 2022). "CYP3A7 expression has also been observed in a subset of the adult population, including pregnant women, as well as in various cancer patients." (PMID 35847040, 2022). "This dataset also serves as a foundation to develop in-silico tools that predict CYP3A7 metabolism and/or inhibition, which will facilitate early drug discovery research for neonates and cancer patients." (PMID 35847040, 2022). "Furthermore, the expression level of CYP3A7, known as the primary fetal CYP3A enzyme, and cancer cell-related genes tended to be high in PXB-cells." (PMID 36678684, 2022).
tumour (3 papers, 1999 to 2020). "RT-PCR showed that both CYP3A5 mRNA and CYP3A7 mRNA were consistently present in both tumour and normal samples, while CYP3A4 mRNA was present in 65% of tumours and 90% of normal samples." (PMID 10206301, 1999). "The use of a CYP3A5-specific antibody allowed us to exclude the expression of CYP3A5 in the tested tumours, but the involvement of CYP3A7 could not be further clarified because of the absence of a specific anti-CYP3A7 antibody." (PMID 14970873, 2004).
infection (2 papers, 2020 to 2022). The state of being infected such as from the introduction of a foreign agent such as serum, vaccine, antigenic substance or organism. "According to the optimized infection condition, COS-1 homogenates were prepared, and the activity of expressed CYP3A4 was measured with luciferin-IPA as a substrate, which is converted to luciferin by CYP3A4 but shows minimal cross-reactivity with CYP3A5 and CYP3A7." (PMID 35295333, 2022).
CYP3A7 also shares sentences with these, for which no sentence is quoted: endometrial cancer (1 paper); nephrotic syndrome (1); poisoning (1).